PRSS22 (serine protease 22)
Description:
Preferentially cleaves the synthetic substrate H-D-Leu-Thr-Arg-pNA compared to tosyl-Gly-Pro-Arg-pNA.
Synonyms: BSSP-4; SP001LA; hBSSP-4
Tractability: Antibody: UniProt places it where antibodies can reach, with high confidence; UniProt predicts a signal peptide or a membrane-spanning region; its Gene Ontology location is reachable by antibodies, with medium confidence.
Gene: Protein-coding gene on chromosome 16 (2,852,728 to 2,858,210, reverse strand). Ensembl gene ENSG00000005001.
Subcellular location: Secreted
Gene Ontology:
Molecular function: peptidase activator activity; protein binding; serine-type endopeptidase activity; serine-type peptidase activity
Biological process: positive regulation of peptidase activity; proteolysis; protein processing
Cellular component: extracellular region
Genetic constraint (gnomAD): Loss-of-function variants: 26 observed, 27.84 expected, observed/expected ratio (o/e) 0.93, 90% interval 0.68 to 1.3. The synonymous counts are far from expectation, so gnomAD's model fits this gene poorly and the ratio says little. Missense variants: 444 observed, 394.59 expected, observed/expected ratio (o/e) 1.13, 90% interval 1.04 to 1.22. Synonymous variants: 217 observed, 164.43 expected, observed/expected ratio (o/e) 1.32, 90% interval 1.18 to 1.48.
Homologues: Orthologues: macaque PRSS22 (85% identical), chimpanzee PRSS22 (82% identical), dog PRSS22 (76% identical), pig PRSS22 (75% identical), mouse Prss22 (74% identical), rat Prss22 (73% identical), guinea pig PRSS22 (72% identical), zebrafish st14a (36% identical), zebrafish st14b (34% identical), zebrafish tmprss15 (33% identical), Drosophila melanogaster Sb (32% identical), Drosophila melanogaster CG1632 (28% identical), and 3 more. Paralogues in human: TMPRSS6 (36% identical), TMPRSS11F (35% identical), ST14 (34% identical), HPN (34% identical), TMPRSS3 (34% identical), PRSS21 (33% identical), TMPRSS11B (32% identical), TMPRSS11D (32% identical), TMPRSS9 (31% identical), TMPRSS13 (31% identical), TMPRSS2 (31% identical), TMPRSS5 (31% identical), and 5 more.
Diseases named in the same sentence as PRSS22 in open-access papers:
PRSS22 is named in the same sentence as 28 diseases in open-access papers, as found by Europe PMC text mining. Sharing a sentence is not in itself a finding about the gene and the disease. The quoted sentences say what the papers report.
breast carcinoma (3 papers, 2022 to 2025). "In breast cancer, PRSS22 is essential for cancer development and progression via triggering of the extracellular signal-regulated kinase 1/2 (ERK1/2) signaling pathway." (PMID 40909962, 2025). "Earlier studies have indicated that PRSS22 contributes to cancer cell development in human hepatocellular carcinoma, that overexpression of PRSS22 facilitated the breast cancer cells invasion and that suppression of PRSS22 was restrictive." (PMID 40909962, 2025).
colon carcinoma (3 papers, 2006 to 2025). "The five colon carcinoma cell lines analyzed expressed PRSS22 mRNA at similar levels to the primary tumors with Caco2 cells expressing the highest levels and T84 the lowest level." (PMID 40909962, 2025). "The predictive efficacy of proteases PRSS3 and PRSS22 mRNA levels for predicting relapse in surgically treated colon cancer (CC) patients was assessed." (PMID 40909962, 2025). "Pairwise comparisons of levels in the primary tumor and the highest lymph node of PRSS3 and PRSS22 mRNAs in colon cancer patients." (PMID 40909962, 2025). "Selection of some of the most suitable mRNAs (TMEM69, RANBP3 and PRSS22) that were assayed in blood samples from normal subjects and patients with colon cancer as possible markers for the presence of epithelial cells in the blood, using reverse transcription – polymerase chain reaction (RT-PCR)." (PMID 17054783, 2006). "Correlations between levels of PRSS3 and PRSS22 mRNAs and CEA, CXCL16, CXCL17, GPR35 V2/3, LGR5, LGR6 and KLK6 mRNA levels in lymph nodes of colon cancer patients." (PMID 40909962, 2025). "Human tryptase-ε/PRSS22, which is highly homologous to rat brain serine protease bsp2, and adenosine monophosphate deaminase 3 (AMPD3) were up-regulated in all 5 human colon cancer tissues compared to the corresponding normal mucosa." (PMID 17112382, 2006).
colorectal cancer (3 papers, 2024 to 2025). A primary or metastatic malignant neoplasm that affects the colon or rectum. "In addition, PRSS22 was also associated with colorectal cancer, revealing its importance in indicating colonic disorders." (PMID 39144720, 2024). "This study pioneers the investigation of PRSS22 mRNA expression in regional LNs as a prognostic biomarker in colorectal cancer patients undergoing curative surgery for cure." (PMID 40909962, 2025). "In colorectal cancer, it is only known that PRSS22 may exhibit differential mRNA expression levels in the blood of colorectal cancer patients compared to normal controls." (PMID 40463392, 2025). "Additionally, interventions targeting PRSS22 and its downstream pathways may open new avenues for personalized treatment strategies, promoting advances in early diagnosis and precision therapy for colorectal cancer." (PMID 40463392, 2025).
hepatocellular carcinoma (3 papers, 2014 to 2025). A malignant tumor that arises from hepatocytes. "In terms of tumors, PRSS22 has been known to be highly expressed in hepatocellular carcinoma and is related to metastasis and invasion." (PMID 36414640, 2022). "Similarly, PRSS22 appears to influence tumor cell migration and invasion in hepatocellular carcinoma." (PMID 40909962, 2025).
gastric cancer (2 papers, 2022 to 2025). A primary or metastatic malignant neoplasm involving the stomach. "A recent study has discovered that a protein called PRSS22 plays a crucial role in the immune evasion of gastric cancer, providing new insights into its treatment." (PMID 41497316, 2025). "In our previous investigation using gene expression microarray (GSE72307), we showed that PRSS22 is upregulated in gastric cancer (GC) tissues with lymph node metastasis (LNM) compared with GC tissues without LNM." (PMID 36414640, 2022).
rectal cancer (2 papers, 2025). A primary or metastatic malignant neoplasm that affects the rectum. "It was worth noting that there was a correlation between PRSS22 expression and the N stage only in rectal cancer, which has also been confirmed in the cohort of our Yangpu Hospital." (PMID 40463392, 2025). "In various tumor cells such as ovarian cancer, lung cancer, and rectal cancer, the PRSS22 expression is higher than the corresponding normal cells, suggesting that its abnormal expression may be related to the occurrence and development of tumors." (PMID 41497316, 2025).
ductal carcinoma in situ (1 paper, 2022). "Compared with ductal carcinoma in situ (DCIS), PRSS22 expression significantly increased in invasive ductal carcinoma (IDC) of the breast." (PMID 36414640, 2022).
liver cancer (1 paper, 2025). An epithelial or non-epithelial malignant neoplasm that arises from the liver. "In breast and liver cancer, PRSS22 is reported to promote tumor progression through the ERK signaling pathway." (PMID 40463392, 2025).
lymph node metastasis (1 paper, 2025). "In subgroups with and without peripheral nerve invasion, age > 65 years, pathological grades II&III&IV, no lymph node metastasis, and T3&T4 staging, increased PRSS22 expression was associated with poor overall survival." (PMID 40463392, 2025).
sarcopenia (1 paper, 2023). Progressive decline in muscle mass due to aging which results in decreased functional capacity of muscles. "Although no studies demonstrate the relationship between the expression of PRSS22, C170rf97, and HLA-DPB15 genes and lean mass, studies show variations in the human leukocyte antigen (HLA) gene polymorphism are related to sarcopenia." (PMID 37123284, 2023).
ulcerative colitis (1 paper, 2025). An inflammatory bowel disease involving the mucosal surface of the large intestine and rectum. "Recent literature has reported that PRSS22 may serve as a biomarker for early diagnosis and dynamic monitoring in ulcerative colitis." (PMID 40463392, 2025).
cancer (7 papers, 2014 to 2025). A tumor composed of atypical neoplastic, often pleomorphic cells that invade other tissues. "Most interestingly, PRSS22 is expressed and released by several types of cancer cell lines including colon adenocarcinomas." (PMID 40909962, 2025). "TIMER database was used to quantify PRSS22 in different cancers as well as the correlation between the PRSS22 expression and the abundance of immune infiltration by gene module." (PMID 41497316, 2025). "Subsequently, we selected 55 pairs of clinical samples for RT-qPCR, Western blotting and IHC, which confirmed the upregulation of PRSS22 expression in cancer tissues at both the mRNA and protein levels." (PMID 40463392, 2025). "This suggests the abnormal expression of PRSS22 in various types of cancer." (PMID 40463392, 2025). "Else, PRSS22 was found to be not expressed in cancer cells (EGFR/FGFR2/MET/VEGFR) of GC patients." (PMID 41497316, 2025).
tumor (7 papers, 2013 to 2025). "The high expression of PRSS22 is not only associated with CRC prognosis but also presents a potential target for developing tumor biomarkers." (PMID 40463392, 2025). "Of particular interest was that PRSS22 was shown to be linked to dysregulation of the tumor immune microenvironment, which might explain the importance of high expression of PRSS22 in LNs." (PMID 40909962, 2025). "What is the mechanism behind the important role that PRSS22 seems to play in tumor progression in CC?" (PMID 40909962, 2025). "The importance of the secreted serine protease, S1 family member PRSS22, in tumor progression is highlighted." (PMID 40909962, 2025). "In spite of all indications of an important role in tumor development and progression, PRSS22 has only been studied to a limited degree in CC." (PMID 40909962, 2025). "Recently, PRSS22 was discovered to be involved in tumor development, however, its detailed biological function and regulatory mechanism in BC are unclear." (PMID 36414640, 2022). "In the GC mouse model, PRSS22 downregulation decreased tumor volume and weight." (PMID 41497316, 2025). "A fraction of CEA-positive tumor cells expressed PRSS22 protein." (PMID 40909962, 2025). "The inhibition of PRSS22 reduced tumor proliferation in the mice model of GC." (PMID 41497316, 2025). "In coculture with AGS and Jurkat cell, si-PRSS22 treatment could reduce the tumor cell growth, migration, Edu positivity, and the immune evasion ability, which would be reversed by suppressing ANXA1." (PMID 41497316, 2025). "It was proved that sh-PRSS22 suppressed the PRSS22 and PD-1 protein expressions and induced ANXA1 protein expression in GC tumor tissues." (PMID 41497316, 2025). "Immunohistochemical analysis with anti-PRSS3, anti-PRSS22, and anti-CEA antibodies applied to H&E(+) LNs demonstrated that a fraction of the tumor cells in the LNs, displayed positive staining for both PRSS3 and PRSS22." (PMID 40909962, 2025). "KLK6, PRSS22, and PRSS3 are all secreted serine proteases, the first two identify CC tumor cells that are useful as tumor markers because they identify aggressive tumor cells." (PMID 40909962, 2025). "PRSS3 and PRSS22 protein expression in CC primary tumors and normal colon tissue was studied by the consecutive staining immunohistochemistry technique using anti-CEA mAb to identify tumor cells." (PMID 40909962, 2025).
PRSS22 also shares sentences with these, for which no sentence is quoted: autism spectrum disorder (1 paper); breast invasive carcinoma (1); Cirrhosis (1); colon adenocarcinoma (1); colonic disorder (1); infection (1); invasive ductal carcinoma (1); kidney (1); lung adenocarcinoma (1); lung carcinoma (1); lung squamous cell carcinoma (1); ovarian carcinoma (1); rectum adenocarcinoma (1); thyroid carcinoma (1); uterine corpus endometrial carcinoma (1).